SP1 (Sp1 transcription factor)
Diseases named in the same sentence as SP1 in open-access papers (continued):
Sharing a sentence is not in itself a finding about the gene and the disease.
breast carcinoma (continued). "With regard to breast cancer, elevated Sp1 was found to regulate thousands of genes that are critically involved in mammary tumorigenesis and metastatic progression, such as vascular endothelial growth factor, urokinase plasminogen activator and its receptor, cyclin D1 and BRCA1." (PMID 25918249, 2015). "Additionally, previous reports showed that activation of SP1 promoted breast cancer development and the metastasis of gastric cancer 33,34." (PMID 25060396, 2014). "To fulfil this task, we evaluated if ERα could localize to lysosomes by employing an ERα antibody, which highlights cytoplasmic ERα in breast cancer cells (i.e., Sp-1 ERα)." (PMID 24736371, 2014). "Similarly, miR-22 targets CDK6, SIRT1, and Sp1, which are genes involved in the senescence program, and induces cellular senescence in both human fibroblast and breast cancer cells." (PMID 24282530, 2013). "Noteworthy, silencing of NCOA3 in MCF-7 cells did not result in complete loss of PLAC1 expression, as basal expression of PLAC1 in breast cancer is not dependent on ERα-signaling but rather on the presence of SP1 and C/EBPβ-2." (PMID 24304549, 2013). "Since estrogen mediated regulation of VEGF expression in ZR-75 breast cancer cells was shown to require Sp1 sites in the core VEGF promoter, we asked whether androgen might behave similarly in prostate cancer cells." (PMID 23369005, 2013). "In conclusion, our data demonstrated the novel finding that DOX could modulate the expression of GCS through the Sp1 site of GCS promoter in ERα-positive breast cancer cells." (PMID 23133636, 2012). "Indole-3-carbinol (I3C) inhibits Sp1-mediated CDK6 expression in breast cancer." (PMID 23148884, 2012). "In conclusion, our data demonstrated the novel findings that DOX could modulate the expression of GCS through the Sp1 site of the GCS promoter in ERα-positive breast cancer cells." (PMID 23133636, 2012). "Treatment with 3,3′-diindolylmethane (DIM) could induce Sp1-mediated p21 expression in breast cancer cells." (PMID 23148884, 2012). "Mechanistically, ErbB2 and v-ras-mediated downregulation of α2-integrin expression has been shown to require the Sp1 transcription factor in human breast epithelial cells, an event that was tied to the disruption of tissue architecture observed in breast cancer." (PMID 22203845, 2011). "We hypothesise that the leptin-induced progression of breast cancer could involve the regulation of IL-1 system expression and activation of NF-κB and/or SP1." (PMID 21139583, 2011). "Therefore, the TNFAIP1/POLDIP2 SFGM is also potentially regulated by STAT1 and Sp1 as well as stimulated by interferon-gamma in breast cancer cells." (PMID 20158880, 2010). "An Sp1 boundary phenomenon has been reported in the BRCA1 promoter of breast cancer cells." (PMID 19912643, 2009). "Moreover, Sp1 levels slowly increase during mice skin tumour progression and Sp1 accumulates in N-methyl-N-nitrosourea-induced mammary tumour cells compared to normal mammary cells." (PMID 19753117, 2009). "Sp1/Sp3 co-transfection results, coupled with the results of Sp3 ChIP assays therefore suggest that Sp3 plays a critical role in the down-regulation of topoisomerase IIα in drug treated breast cancer cells." (PMID 17511886, 2007). "Ursolic acid treatment could significantly promote SP1 expression in breast cancer cells." (PMID 34568078, 2021). "Moreover, we observed the colocalization of TIM with Sp1 in the breast cancer cells via ICC." (PMID 33093451, 2020). "However, the role of Sp1 in breast cancer is still controversial." (PMID 33093451, 2020).
breast carcinoma (continued). "It has been reported that SP1 could trans-activate TS expression in MCF7 breast cancer cells." (PMID 32726929, 2020). "In addition, the correlation analysis of RNA-seq data of 422 breast cancer samples in TCGA database infers that Sp1 could activate the TMBIM6 expression." (PMID 31336725, 2019). "Currently, how leptin activates SP1 in breast cancer cells is unknown." (PMID 21139583, 2011). "INSR is activating PI3K, MAPK, and ERK signaling and has been linked to several tumors including leukemia and PPARG can bind to AP2-ɑ and SP1 and decrease the upregulation effect of AP2-ɑ on INSR in breast cancer." (PMID 41168841, 2025). "In general, these data showed that exosomal SP1 played an indispensable role in activating the TLR4‐NFκβ‐IL‐1β pathway of neutrophils, thereby promoting lung metastasis of breast cancer." (PMID 39630109, 2025). "Under hypoxic conditions, specificity protein 1 (SP1) binds to the vascular permeability factor (VPF)/VEGF promoter and promotes angiogenesis in breast cancer cells." (PMID 40191727, 2025). "These include EMT (TWIST1, SNAIL1, RUNX1, RUNX2, HIF1, and NOTCH1), breast cancer maintenance (OCT4, SP1, GATA1, ATF1, FOXO3a, ELK1, VDR, and NRF1), pro-metastatic responses (SMAD2/3, HNF1a, GLI1, NANOG, YY1, MYB1, and AP1), and immune modulation (STAT1/3)." (PMID 38398186, 2024). "TGFβ-induced EGFR upregulation in breast cancer cells can be mediated by the canonical SMAD3 and ERK/SP1 signaling pathways." (PMID 39468555, 2024). "Studies have shown that Sp1 can directly bind to the promoter region of the PCK1 and controls the proliferation of breast cancer cells by interacting with insulin-like growth factors I receptor, enhancing their transcriptional activity." (PMID 38791477, 2024). "Therefore, targeting Sp1-mediated transcriptional regulation may be a potential therapeutic strategy, but more investigations are needed to understand TFs and hub gene interactions in regulating breast cancer liver metastasis." (PMID 38791477, 2024). "Several transcriptional activators have been identified to regulate hTERT expression in breast cancer cells, including c-MYC, STAT3, NF-κB, ETS2, ERα, Sp1, KLF4, and ZEB1/YAP, among others." (PMID 37612721, 2023). "For this, we tested cell death in presence of Sp-1, an autophagic inhibitor that effectively inhibited autophagosomes induced by ICRP in breast cancer and leukemic cell lines." (PMID 37223080, 2023). "Our study has made groundbreaking progress in identifying key transcription factors, such as SP1, E2F1, and SIN3A, as well as kinases, including MAPK14, CSNK2A1, and CDC2, whose role in breast cancer progression is paramount." (PMID 38084295, 2023). "These functions of miR-7 in breast cancer (BC) can be diminished by the expression of lncRNA TINCR, which is enhanced by the Sp1 transcription factor." (PMID 37384249, 2023). "It has been proven that butyrate-treated cells increase Sp1 and Sp3 occupation at the ATP2A3 promoter and increase ATP2A3 mRNA expression in gastric and breast cancer cell lines." (PMID 35893896, 2022). "Incoherence to breast cancer restricts the cell proliferation, migration, and invasion of gastric cancer and induces apoptosis by targeting ITGB3, Rac1, and Sp1 mRNAs." (PMID 35511336, 2022). "In breast cancer cells, zinc finger E-box binding homeobox 1 (ZEB1) activated VEGFA transcription through enhancing SP1 recruitment to VEGFA promoter." (PMID 36467048, 2022). "Recent studies showed HIF-1 signaling was involved in lymphatic invasion through induction of platelet-derived growth factor B (PDGF-B) in breast cancer, vascular endothelial growth factor C (VEGF-C) and SP1 in ESCC." (PMID 35752862, 2022).
breast carcinoma (continued). "TIMELESS promoted breast cancer progression by activating MYC and regulated cancer cell progression via the Sp1/ACER2/S1P axis." (PMID 35715407, 2022). "In this study, we demonstrate that SREBP1 binds to the promoter, and induces the expression of GS resulting in lipid droplet (LD) formation through O-GlcNAc-Sp1/SREBP1/ACC1 signaling in liver and breast cancer cells." (PMID 34575972, 2021). "Subsequently, O-GlcNAc-Sp1 transcriptionally upregulates the expression of SREBP1, resulting in a feedforward loop that increases lipogenesis and LD formation in liver and breast cancer cells." (PMID 34575972, 2021). "Another study revealed that TIM regulated the sphingolipid metabolism through Sp1/ACER2/S1P axis, promoting the tumor cell growth of breast cancer." (PMID 34490127, 2021). "This study indicates that GS promotes Sp1 O-GlcNAcylation, activating Sp1 to increase SREBP1/ACC1 expression and LD formation in liver and breast cancer cells." (PMID 34575972, 2021). "STAT3 also stimulates the expression of high Ras Homolog Family Member U (RhoU) by collaborating with Specificity Protein 1 (SP1), leading to breast cancer cell migration." (PMID 34488773, 2021). "Metformin regulates transcription factor Sp1 to reduce HMGA2 activation, leading to the inhibition of breast cancer growth." (PMID 32031335, 2020). "High expression of TIM in breast cancer predicts poor prognosis and TIM regulates tumor cell growth and sphingolipid metabolism through Sp1/ACER2/S1P axis." (PMID 33093451, 2020). "E2/ERα has been reported to combine with C/EBPβ/SP1 and induce transcriptional activation of the generic hPIII promoter, activating PRLR expression in MCF-7 breast cancer cells." (PMID 33173437, 2020). "Previous studies showed that SP1 can modulate many lncRNAs like LINC00673120, SPRY4-IT1121, LUCAT1122, and FTH1P3123 in a variety of malignancies in addition to breast cancer." (PMID 32929060, 2020). "SP1, which is reported as a transcriptional activator of TIMP-2 gene in breast cancer, was also found as a candidate target gene of miR-130b 41,42." (PMID 31061410, 2019). "In a breast cancer model, through its direct interaction with its mRNA targets CDK6, SIRT1 and Sp1, which are genes involved in senescence, miR-22 has been able to suppress tumor growth." (PMID 31640796, 2019). "Our data suggested a crucial role of TINCR-miR-7-KLF4 axis in human breast cancer and up-regulation of ceRNA TINCR by SP1 contributes to tumorigenesis in breast cancer." (PMID 29614984, 2018). "Downregulation of Sp1 or Smad3 significantly inhibited the TGF‐β‐induced enhancement of the migration and invasion abilities of two breast cancer cells." (PMID 29215776, 2018). "Canonical Smad3 signaling and ERK/Sp1 signaling pathways are required for the TGF‐β‐induced upregulation of EGFR and the enhancement of migration and invasion abilities of breast cancer cells." (PMID 29215776, 2018). "Although SP1 and SP3 has been investigated in breast cancer, the detailed mechanism by which SP1 and SP3 regulate progression of breast cancer requires to be further investigated." (PMID 30386180, 2018). "In parallel, the RT-qPCR assay revealed that expression levels of SP1 and SP3 were declined in miR-506 overexpressed breast cancer cells relative to that in NC mimic cells." (PMID 30386180, 2018). "In context with the regulatory role of miR-27a/b in ER+ breast cancer, ZBTB10 is a major inhibitor of Sps, including Sp1." (PMID 30214383, 2018). "To test this possibility, we stimulate the breast cancer cells with TGF‐β and determined the Sp1 expression through RT‐PCR and western blot." (PMID 29215776, 2018).
breast carcinoma (continued). "In another motif combination predicted in both breast cancer and colorectal cancer, KLF6 and SP1, these two TFs together initiate the transcription of CERS2 in human prostate carcinoma cells." (PMID 28684851, 2017). "The relevance of Sp1 and Sp3 in estradiol regulation of VEGF in breast cancer was demonstrated by binding assays in vitro (by EMSA) and in vivo (by ChIP)." (PMID 28394264, 2017). "For example, in breast cancer, FUT4 transcription is regulated by HSF1 and Sp1 to inhibit cell proliferation; in HaCaT cells, FUT4 level is lower due to the higher methylation of CpG island in FUT4 promoter." (PMID 26094873, 2015). "In mammary carcinoma, Brg-1, a SWI/SNF chromatin remodeling complex ATPase, was shown to interact with Sp1 to activate SPARC transcription." (PMID 25657638, 2014). "Our data uncover a novel mechanism for BCL9-2 as co-factor, which acts together with Sp1 and regulates ER transcription through the proximal ESR1 gene promoter in breast cancer cells." (PMID 25149534, 2014). "In ZR-75 breast cancer cells, estrogen regulation of VEGF expression is thought to act through ER- α/Sp1 and ER- α/Sp3 interactions with GC-rich motifs." (PMID 23369005, 2013). "Initially, the functional interaction between BRCA1 and Sp1 was suggested to regulate the IGF-I-R, a receptor overexpressed in most breast cancers that serves as an antiapoptotic factor." (PMID 20614009, 2010). "In contrast, we show in this report, using ChIP experiments, that Sp1 binds the MsrB1 promoter region in both high-expressing MCF7 and low-expressing MDA-MB231 breast cancer cells." (PMID 17519015, 2007). "Moreover, it was demonstrated in breast cancer cells that lncRNA MACC1-AS1 can form a complex with DEAD-Box Helicase 5 (DDx5), recruiting Specificity Protein 1 (SP-1) to the MACC1 core promoter and ultimately leading to an increase in MACC1 expression." (PMID 39580452, 2024). "For example, in breast cancer, two TBX2 complexes have been identified: the TBX2-CoREST complex targets N-Myc Downstream Regulated 1 (NDRG1) by recruiting TBX2 to the NDRG1 promoter via Sp1 transcription factor (SP1)." (PMID 38965548, 2024). "Following this, O-GlcNAc-Sp1 enhances the transcription of SREBP1, creating a cycle of reinforcement that boosts the production of lipids and the formation of lipid droplets in both liver and breast cancer cells." (PMID 39228402, 2024). "In addition, ETS2 、ERαand Sp1, KLF4, and ZEB1/YAP have also been identified as regulators of hTERT transcription in breast cancer cells." (PMID 37612721, 2023). "SP-1 can bind with FOXF2 promoter region and block the DNA methylation of FOXF2 in breast cancer cells, leading to promotion of cell proliferation in basal-like breast cancer." (PMID 35620052, 2022). "Although the relevance of SP1 mRNA level with the prognosis of breast cancer and colon adenocarcinoma was not statistically significant, the overall tendency was distinct." (PMID 34257529, 2021). "In breast cancer, SP1 stimulates non-classical Wnt response gene subgroups to shorten the overall survival of patients." (PMID 34257529, 2021). "Finally, it was also reported that SP1 and its analogue FTY720 increase radiation sensitivity of human breast cancer cells in vitro." (PMID 34336090, 2021). "Chromatin immunoprecipitation (ChIP) assay was performed to show the binding of Sp1 to HMGA2 promoter in breast cancer cells with or without metformin treatment." (PMID 32031335, 2020). "Using pathway enrichment analysis, we found that SP1 was involved in multiple pathways enriched by known cancer genes, such as the transforming growth factor (TGF)-beta signaling pathway and choline metabolism in cancer and breast cancer." (PMID 33488678, 2020).
breast carcinoma (continued). "For example, SP1 is essential for the full transcriptional activity of ER alpha and their interactions will control the transcription of IGF-IQ gene whose dysregulated expression have pathologic consequences with relevance in breast cancer aetiology." (PMID 30957858, 2019). "To verify whether Sp1 is essential for the transcriptional activation of EGFR, we treated breast cancer cells with a Sp1 inhibitor MTM." (PMID 29215776, 2018). "Canonical Smad3 signaling and ERK/Sp1 signaling pathways were also crucial for the TGF‐β‐induced upregulation of EGFR expression and the enhancement of migration and invasion abilities of breast cancer cells." (PMID 29215776, 2018). "Our data reveal a novel axis of miR-506/SP3/SP1/DNMT1/MEG3 in regulating migration and invasion of breast cancer cell lines, which provide rationales for developing effective therapies to treating metastatic breast cancers." (PMID 30386180, 2018). "Although miR-375-mediated Sp1 regulation has not been verified in breast cancer models, this potential mechanism highlights a facet of miR-375-associated estrogen/ERα signaling regulation." (PMID 30214383, 2018). "In addition, another study revealed that the PI3K/AKT pathway promoted the expression of IGFBP2 in MCF-7 breast cancer cells, and LY294002 (a PI3K inhibitor) directly reduced IGFBP2 production via the SP-1, which is a transcription factor involved in IGFBP2." (PMID 28036255, 2017). "It has also been reported in colon, gastric, pancreatic, and breast cancers that Sp1 is overexpressed, whereas minimal to no Sp1 expression is detected in normal differentiated cells." (PMID 28484232, 2017). "Consistent with this, the ERE-900 was found essential for the repressive action of estrogen in MCF-7 and in BT-474 breast cancer cells, while deletion of the Sp1-1020 site slightly diminished but did not abolish the down-regulation by estrogen." (PMID 27764788, 2016). "Similarly, in breast cancer cells, the estrogen receptor enhances IGF-IR gene promoter activity via interactions with Sp1 and WT1." (PMID 25884514, 2015). "miR-335 appears to control growth by blocking cell proliferation by targeting certain genes; e.g., RASA1 in rat epididymal development, SP1 and Bcl-w in non-small cell lung cancer, SOX4 and TNC in breast cancer, ROCK1, MAPK1, and LRG1 in neuroblastoma, and Rb1 in U2OS osteosarcoma cells." (PMID 26204513, 2015). "Sp1 has previously been confirmed to be an essential modulator of the regulation of HMGA1 promoter activity and we determined the involvement of Sp1 in the TGF-β1-induced HMGA1 expression in breast cancer cells." (PMID 25572132, 2015). "Interestingly, in ER- breast cancer, ESR1 (ERα), RELA, SP1, and AR exhibit the highest degree in the network." (PMID 25996148, 2015). "It has been reported that miR-335 suppresses breast cancer metastasis by targeting SOX4 and Tenascin C, small cell lung cancer metastasis by targeting IGF1R and RANKL, and induces apoptosis of breast cancer cells by regulating ERα, IGF1R, SP1, and ID4." (PMID 26098312, 2015). "In conclusion, to the best of our knowledge, the present study provides the first evidence of the role of TGF-β1 in the regulation of HMGA1 expression in breast cancer cells and PI3K signaling and Sp1 were found to be involved in the TGF-β1-induced expression of HMGA1." (PMID 25572132, 2015). "Similarly, the top hub TFs we found in the integrated network such as SP1, SP2, TCF12, MYC, JUN and EGR2, were also well-known regulators in breast cancer." (PMID 26763900, 2015).